E2F5 (E2F transcription factor 5)
Diseases named in the same sentence as E2F5 in open-access papers (continued):
Sharing a sentence is not in itself a finding about the gene and the disease.
gastric cancer (5 papers, 2015 to 2024). A primary or metastatic malignant neoplasm involving the stomach. "This relationship suggests a potential E2F5/UBE2T axis in gastric cancer, opening new avenues for the diagnosis and treatment of this malignancy." (PMID 39791716, 2024). "For further confirmation, the Western blot results show that the protein expression of E2F5 was significantly higher in gastric cancer cell lines compared with the normal cell lines." (PMID 34947956, 2021). "Alteration in the expression of E2F5 results in the activation of the expression of BCL2 in gastric cancer cell lines." (PMID 34947956, 2021). "The results revealed that relative mRNA expression of E2F5 was higher in gastric cancer cell lines compared with normal cell lines (* p < 0.05)." (PMID 34947956, 2021). "This study illustrated that HDACi downregulates the expression of HDACs and E2F5 in gastric cancer cell lines." (PMID 34947956, 2021). "For the investigation of the mechanistic role of E2F5 in gastric cancer, we observed that the level of E2F5 in gastric cancer cell lines using qRT-PCR was appreciably upregulated." (PMID 34947956, 2021). "HDACi and knocking down of E2F5 as tumor suppressors inhibited cell proliferation, migration invasion, and blocked the cell cycle in gastric cancer cells by suppressing BCL2." (PMID 34947956, 2021). "To explore the function of HDACs in gastric tumors, we investigated the expression of HDACs and E2F5 at both mRNA and protein levels in gastric cancer cell lines (MGC-803, MKN28, MKN45, KATO III, AGS, and N87) and a normal cell line (GES-1)." (PMID 34947956, 2021). "Similarly, the present study also determined the mRNA expression of E2F5 in gastric cancer cell lines." (PMID 34947956, 2021). "The results revealed that HDACs regulate the expression of E2F5 gastric cancer cell lines." (PMID 34947956, 2021). "In gastric cancer, miR-106b-5p could promote the cell cycle by down-regulating target gene expression of p21 and E2F5." (PMID 25714014, 2015). "Such consequences suggest that HDAC and E2F5 might act as crucial biomarkers in gastric cancer." (PMID 34947956, 2021). "MiR-17 family clusters are emerging as key modulators of TGF-βtumor suppressor signaling in gastric cancer, through regulation of p21, E2F1–3 and E2F5 target gene expression." (PMID 25646628, 2015). "Our findings showed that HDAC inhibitors E2F5 and BCL2 are the therapeutic candidates for gastric carcinomas, which agrees with the hypothesis of HDAC being overexpressed in gastric cancer cell lines." (PMID 34947956, 2021). "Furthermore, miRNAs differentially expressed in gastric cancer were able to regulate expression of E2F1, E2F2, E2F5 and E2F7, indicating that miRNAs-altered expression of E2Fs proteins is important factors in gastric cancer development or progression." (PMID 25646628, 2015). "Furthermore, miRNAs (miR-125a-5p, miR-331–3p, miR-17, miR-150, miR-155, miR-27b, miR-31, miR-92a and miR-509–5p), which differentially expressed in gastric cancer, were found to regulate expression of E2F1, E2F2, E2F5 and E2F7 in this study." (PMID 25646628, 2015). "The Western blot results showed that knocking down of E2F5 decreased the protein expression of E2F5 and BCL2 in gastric cancer cell lines compared with the negative control." (PMID 34947956, 2021).
pancreatic cancer (5 papers, 2016 to 2023). "MicroRNA 1179 was found to inhibit proliferation and invasion in pancreatic cancer cells through the inhibition of E2F5." (PMID 38028548, 2023). "Several other reports have demonstrated miRNA playing a biological role in pancreatic cancer pathways, such as those targeting TXNIP-Mediated HIF1α, E2F5, TGF-β2/TGF-βRIII, HIF1α, and PTEN." (PMID 35740894, 2022).
retinoblastoma (4 papers, 2018 to 2024). A malignant tumor that originates in the nuclear layer of the retina. "Their findings showed that miR-613 acts as a tumor suppressor in retinoblastoma by downregulating E2F5." (PMID 36619866, 2022). "Their data supported the idea of targeting the miR-613/E2F5 axis as a potential therapeutic approach for retinoblastoma." (PMID 36619866, 2022). "A series of canonical pathways, including those involved in Rb (Retinoblastoma)/E2F cell cycle (Rb, E2f2, E2f3, E2f5, Cdk6, DHFR), Notch (Dll1, Notch 2, Jag1), Wnt (Wnt, Axin2, Wisp2/Ccn5) and NF-κB (Ikbip) were found to participate in this network." (PMID 30742662, 2019). "Previous studies have shown that loss of E2f1 and E2f3, but not E2f5, prevents retinoblastoma formation in Rb1-deficient mice." (PMID 30220967, 2018).
colon cancer (3 papers, 2020 to 2025). "E2F5 was a bona fide target gene of miR-34a and the restoration of E2F5 significantly antagonized the suppression of colon cancer cell proliferation and invasion." (PMID 32117628, 2020). "Our study demonstrated that the expression of E2F5 was significantly increased in colon cancer tissues, however, the level of which did not affect the tumor stage and survival rate of patients with colon cancer." (PMID 32117628, 2020). "Our studies indicated that the deregulation of E2F1, E2F2, E2F3, E2F5, E2F7 and E2F8 in colon cancer tissues might play a vital role in colon cancer oncogenesis, which could be promising diagnostic biomarkers for LUAD." (PMID 32117628, 2020). "In colon cancer tissues, hsa_circ_001988 expression reduced and hsa_circ_001569 negatively correlated with miR-145 as a sponge by attenuating BAG4, E2F5, and FMNL2 expressions." (PMID 36313671, 2022). "Our study implied that E2F3, E2F4, E2F7 and E2F8 are potential targets of precision therapy for patients with colon cancer while E2F1, E2F2, E3F3, E2F5, E2F7 and E2F8 are potential biomarkers for the diagnosis of colon cancer." (PMID 32117628, 2020).
esophageal squamous cell carcinoma (3 papers, 2016 to 2021). Esophageal squamous cell carcinoma (ESCC) is a type of esophageal carcinoma (EC) that can affect any part of the esophagus, but is usually located in the upper or middle third. "Additionally, E2F5 was identified as an independent prognostic factor in esophageal squamous cell carcinoma; the 5-year survival rate of the E2F5-positive group was 39.3%, which was significantly lower than that of the E2F5-negative group (83.8%)." (PMID 34476219, 2021).
Hydrocephalus (3 papers, 2008 to 2021). Hydrocephalus is an active distension of the ventricular system of the brain resulting from inadequate passage of CSF from its point of production within the cerebral ventricles to its point of absorption into the systemic circulation. "Knockouts of E2f5, a member of a family (E2f1–E2f6) of transcriptional regulators and FoxJ1, a member of the forkhead-box (Fox)/winged helix gene family, have been associated with defective choroid plexus function resulting in hydrocephalus." (PMID 19114013, 2008). "Knockout of genes expressed in the CPe, such as E2f5, a member of a family (E2f1–E2f6) of transcriptional regulators, FoxJ1, a member of the forkhead-box (Fox)/winged helix gene family, and p73, have been associated with hydrocephalus." (PMID 19114013, 2008). "However, the E2f5–/– mice die before reaching adulthood due to excessive cerebrospinal fluid production and consequently non-obstructive hydrocephalus." (PMID 34746136, 2021).
male infertility (3 papers, 2017 to 2022). The inability of the male to effect fertilization of an ovum after a specified period of unprotected intercourse. "Interestingly, conditional deletion of E2F4 in the EDs in combination with heterozygous mutation of E2F5 (E2F4fl/fl/E2F5+/−;Villin-Cre) results in defective MCCs and male infertility." (PMID 35159149, 2022). "The male infertility observed in mice lacking both E2F4 and E2F5 has been proposed to result due to defects solely in the development of MCCs in the ED and future work will be needed to fully characterize this defect in Ccno-/- mice." (PMID 29245899, 2017).
osteosarcoma (3 papers, 2019 to 2023). A usually aggressive malignant bone-forming mesenchymal neoplasm, predominantly affecting adolescents and young adults. "Furthermore, although prior studies have shown that E2F regulation of cIAPs and E2F1 directly promotes MAP3K14 gene expression in osteosarcoma cells, we report for the first time that the E2F transcription factors E2F4 and E2F5 play a role in regulating NIK transcription and expression." (PMID 36945490, 2023).
breast tumors (2 papers, 2010 to 2019). "Along with chromosomal amplifications and overexpression of the E2F5 gene as detected in breast tumors suggests that E2F5 deregulation may have a role in human tumor development." (PMID 20181230, 2010).
melanoma (2 papers, 2020). A malignant, usually aggressive tumor composed of atypical, neoplastic melanocytes. "Moreover, E2F1 and E2F5 were inversely correlated with miR-205 in melanoma cell lines as the expression of these two proteins was elevated in melanoma cell lines while miR-205 was found to be suppressed." (PMID 32854238, 2020). "Another E2F family member, E2F5, similar to E2F1, is an oncogenic cell cycle regulator that is also found to be amplified in numerous tumors, including melanoma." (PMID 32722415, 2020). "miR-205 in melanoma cell lines inversely correlates with the expression levels of E2F1 and E2F5." (PMID 32722415, 2020).
neuroblastoma (2 papers, 2022 to 2025). Neuroblastoma (NB) is the most common solid, extracranial childhood tumor. "E2F5 had been shown to promote the proliferation of neuroblastoma cells, thus proving to be an oncogene in neuroblastoma." (PMID 34784267, 2022). "In neuroblastoma, MYCN-induced E2F5 enhances cell proliferation by regulating cell cycle progression." (PMID 40862719, 2025).
ovarian tumor (2 papers, 2010 to 2020). "E2F5 was found to be upregulated (5 fold) in early and late stage ovarian tumours." (PMID 20181230, 2010).
adenoma (1 paper, 2024). A neoplasm arising from the epithelium. "Adenomas had significantly increased expression of transcription factors E2f5 and Tcf712, Wnt family receptor Fzd2, transcriptional regulator Nfatc3, regulator of the gamma secretase complex Psenen, and Rb." (PMID 38334641, 2024).
Anxiety (1 paper, 2023). Intense feelings of nervousness, tension, or panic often arise in response to interpersonal stresses. "Here, we have delineated E2f5/c-Myc interaction as an interactive signaling network linking TGF-β, and MAPK, signaling pathways together during anxiety regulated by anxiolytic miRs." (PMID 36979479, 2023). "Our finding determined that E2F5 acts as a hub target gene for anxiolytic miRs, and its effect may be mediated by its interaction with c-Myc and impact on other cellular pathways like MAPK and further suppression/activation of key regulators in anxiety-related behavior." (PMID 36979479, 2023). "However, a potential mechanism by which E2F5 and/or c-MYC regulate anxiety-related disorders remain unknown, and the role of E2F5/c-MYC interaction in regulating downstream genes involved in anxiety has not been addressed so far." (PMID 36979479, 2023).
co-infection (1 paper, 2021). "Depletion of circCDK13 or E2F5 facilitated cell apoptosis, and this effect was further enhanced by co-infection of LV-shE2F5 and LV-shcircCDK13." (PMID 33390186, 2021).
cyst (1 paper, 2010). A sac-like closed membranous structure that may be empty or contain fluid or amorphous material. "To answer the question, after identification of a cyst using ultrasound, we used a combination of CA125 and E2F5." (PMID 20181230, 2010).
depression (1 paper, 2025). "E2F5 messenger RNA was recently proposed as a target for 3 anxiolytic microRNAs, while plasma tau (MAPT) has shown association with measures of depression in older, cognitively intact adults." (PMID 40697488, 2025).
diabetes (1 paper, 2022). "Similarly, miR-217 and miR-132 exert their anti-proliferative and anti-migratory effects on VSMCs under high glucose conditions mimicking diabetes via suppression of ROCK1 and E2F transcription factor 5 (E2F5), respectively." (PMID 36614057, 2022).
esophageal cancer (1 paper, 2021). A primary or metastatic malignant neoplasm involving the esophagus. "Ectopic miR-544 and miR-338-5p could overcome DDP resistance of esophageal cancer via targeting and down-regulating oncogene E2F transcription factor 5 (E2F5) and fermitin family homolog 2 (FERMT2)." (PMID 34881242, 2021).
Ewing sarcoma (1 paper, 2013). A small round cell tumor that lacks morphologic, immunohistochemical, and electron microscopic evidence of neuroectodermal differentiation. "Because IER3 is a modulator of apoptosis through TNFalpha or FAS-signaling, the balance between its repression (through MYC, E2F2 and E2F5 that are EWS-FLI1 induced and therefore disease specific) and activation (through NFkB) may be of particular interest in Ewing sarcoma." (PMID 23935076, 2013).
gastric tumor (1 paper, 2021). "In conclusion, the knowledge gained from our study is that HDAC inhibitors impede gastric tumor cell migration, proliferation, and suppression of other cellular functions of tumors by regulating E2F5 through direct BCL2 targeting." (PMID 34947956, 2021). "Moreover, the inhibition of HDAC appearance can relatively invalidate the E2F5-mediated results in gastric tumor cells, and re-establish cell proliferation invasion and migration." (PMID 34947956, 2021).
intestinal cancer (1 paper, 2018). "Increased expression of E2F5 was correlated with favourable OS in all GC patients, HR = 0.64 (0.54–0.076), P=2.8 × 10−7, intestinal cancer patients, HR = 0.56 (0.41–0.76), P=0.00043 and diffuse GC patients, HR = 0.58 (0.41–0.81), P=0.0013." (PMID 30487158, 2018).
leukemia (1 paper, 2024). A malignant (clonal) hematologic disorder, involving hematopoietic stem cells and characterized by the presence of primitive or atypical myeloid or lymphoid cells in the bone marrow and the blood. "E2F5 is a cell cycle regulator highly expressed in a variety of cancers, while knockdown of E2F5 can interrupt the growth of leukemia cells." (PMID 39129784, 2024).
liver failure (1 paper, 2021). A liver disease characterized by the liver losing or has lost all of its function. "Therefore, targeting the E2F5/TFDP1-BRG1-MYCN axis may prove effective in the treatment of liver failure." (PMID 34746136, 2021).
lung adenocarcinoma (1 paper, 2018). A carcinoma that arises from the lung and is characterized by the presence of malignant glandular epithelial cells. "E2F5 is significantly upregulated in lung adenocarcinoma, with fold changes of 4.085 and 2.208 in Bhattacharjee’s dataset and Stearman’s dataset, respectively." (PMID 29754146, 2018). "The results indicated that the expression levels of E2F1, E2F2, E2F3, E2F5, E2F6, E2F7, and E2F8 were higher in lung adenocarcinoma and squamous cell lung carcinoma tissues than in lung tissues, whereas and the expression level of E2F4 was lower in the former than in the latter." (PMID 29754146, 2018).
meningioma (1 paper, 2016). A generally slow growing tumor attached to the dura mater.
oligodendroglioma (1 paper, 2020). A well-differentiated (WHO grade II), diffusely infiltrating neuroglial tumor, typically located in the cerebral hemispheres. "In the French Brain Statistics, E2F5 was overexpressed in anaplastic oligodendroglioma versus normal tissues with a fold change of 2.425." (PMID 33381564, 2020).
serous carcinoma (1 paper, 2010). "Similar to tissue array results endometroid and serous carcinoma showed increased over expression of E2F5 compared to other types of OEC (cc = 0.47)." (PMID 20181230, 2010). "Relatively high expression of E2F5 was found in endometroid and serous carcinoma than in other types of OEC." (PMID 20181230, 2010).
teratocarcinoma (1 paper, 2013). A germ cell tumor characterized by the presence of an embryonal carcinoma component and a teratoma component. "They reported that human stem cells and teratocarcinoma cells show a selective reduction in the expression of E2F1, E2F2, E2F3 and p105 (encoded by NFKB1) and enhanced expression of E2F4, E2F5, E2F6 and p130 (encoded by RBL2) compared with human normal somatic IMR90 cells." (PMID 24355041, 2013).
thyroid tumor (1 paper, 2023). A benign or malignant neoplasm affecting the thyroid gland. "Although sustaining proliferative signaling is a hallmark of cancer, the unique mechanism among these thyroid tumors indicates that E2F transcription factors, specially E2F5, may have an important role in this process." (PMID 36896180, 2023).